MYC (MYC proto-oncogene, bHLH transcription factor)
Diseases named in the same sentence as MYC in open-access papers (continued):
Sharing a sentence is not in itself a finding about the gene and the disease.
glioma (continued). "The ethyl ester form of the FTO inhibitor Meclofenaic (MA2) inhibits FTO and enhances the effect of the chemotherapeutic drug temozolom by targeting the MYC-miR-155/23a cluster-MXI1 feedback circuit in gliomas anti-tumor effects." (PMID 35707365, 2022). "The presence of this mutation in glioma upregulates HIF-1a expression, which decreases c-MYC activity, resulting in a consequential decline in miR-20a, is responsible for glioma cell proliferation and resistance to temozolomide (TMZ) treatment." (PMID 36321132, 2022). "BRD4 inhibition has been shown to inhibit transcriptional activation of the oncogene c-MYC, which has been poised as particularly important for progression from low grade to high grade IDHmut glioma." (PMID 35467128, 2022). "Inhibition of MYC/MAX alone significantly reduced cell viability to 12%, which concords with the reported contribution of MYC to glioma stem cell maintenance." (PMID 36361720, 2022). "MZF1 overexpression is proposed to contribute to the proliferation and growth of gliomas through the regulation of c-MYC." (PMID 36499054, 2022). "Consistent with the previous results, the protein level of PTTG1 was significantly increased in glioma in comparison to peritumor tissue, while the level of MYC was decreased in tumor." (PMID 36527013, 2022). "Our data suggest that CTD treatment diminishes glioma proliferation, which is associated with the down-regulation of MZF1 and c-MYC." (PMID 36499054, 2022). "In order to investigate the influence of PTTG1 and MYC on the invasion of glioma cells, we conducted a 3D collagen spheroid invasion assay." (PMID 36527013, 2022). "MYC-expressing glioma cells have previously been shown to undergo apoptosis upon glutamine withdrawal that can be rescued by asparagine supplementation." (PMID 35945217, 2022). "In summary, these data indicated that FTO regulated the feedback loop in glioma cells by targeting MYC transcripts." (PMID 35625706, 2022). "MYC was also reported to be highly expressed in GBM, and overexpression of MYC in gliomas is related to increasing tumor grade." (PMID 36361720, 2022). "To explore the effect of PTTG1 and MYC on glioma cell survival and invasion, we transfected cells with siRNA to downregulate PTTG1 and MYC." (PMID 36527013, 2022). "Consistently, many studies have demonstrated that the activation of the cell cycle, PI3K-AKT, MTORC1, NOTCH, and MYC pathways enhances the progression of glioma." (PMID 34631793, 2021). "Another identified factor, MXI1, was reported as a tumor suppressor negatively regulating c-MYC and an inhibitor of glioma proliferation." (PMID 34131149, 2021). "Of importance to glioma, PVT1 has been implicated in regulating levels the proto-oncogene MYC to promote tumorigenesis." (PMID 33926464, 2021). "In patients with glioma, there is an inverse correlation between survivability and the expression of another RNA, miR-135a-5p, which suppresses the expression of the MYC gene." (PMID 34440124, 2021). "The MYC gene has been reported to be highly expressed in gliomas, which can promote cell growth and increase cell sugar fermentation." (PMID 34744739, 2021). "In the cancers of the nervous system, glioma and medulloblastoma, miRNA miR-33b-5p disturbs the regulation of MYC expression." (PMID 34440124, 2021). "In nervous system tumors, gliomas and medulloblastomas, the regulation of MYC gene expression was found to be impaired by the binding of miR-33b-5p ceRNA DANCR." (PMID 34440124, 2021). "Another study reported that LPP-AS2 regulates EGFR expression by sponging Mir-7-5p as a ceRNA and combination of the promoter region of LPP-AS2 with c-MYC contributes to the development of glioma." (PMID 34425868, 2021). "CHIP induces the ubiquitination and degradation of the oncoprotein c-MYC in glioma cells; its knockdown magnifies the metastatic properties of these cells." (PMID 33665742, 2021).
glioma (continued). "As we also observed differential expression of well-known cancer-related genes, such as upregulation of the MYC oncogene in the H3.1/H3.2high samples, we asked whether the expression of the canonical histone H3 proteins might be associated with different degrees of glioma aggressiveness." (PMID 34771425, 2021). "The role of MYC in glioma has been well established, both in vivo and in vitro, such that MYC inhibition suppresses glioma formation, restricts glioma cell proliferation and improves survival." (PMID 33926464, 2021). "OCT4 and MYC are two of the canonical stem cell factors responsible for progression of a wide range of solid tumors, particularly glioma." (PMID 34646821, 2021). "Knockdown of BPTF impairs tumor development with inactivation of the c-MYC and/or c-Myc target genes transcriptional program in preneoplastic pancreatic acinar cells and high-grade glioma." (PMID 34736517, 2021). "The expression of H19 non-coding RNA is induced by c-Myc product, a member of the MYC proto-oncogene family, which promotes development of glioma." (PMID 34081618, 2021). "Cancer transcription factor MYC up-regulates the mRNA expression of hnRNPA1 and hnRNPA2 in gliomas, which promotes the synthesis of pyruvate kinase M subtype 2 (PKM2) and participates in glycolytic transformation." (PMID 33488680, 2020). "Previous studies have provided sufficient evidence that MYC is up‐regulated in gliomas and its forced down‐regulation has been shown to promote cell apoptosis and reduce the formation of xenograft tumours in vivo." (PMID 32916774, 2020). "In malignant glioma with primitive neuroectodermal components (MG-PNET), a rare type of brain tumor that most likely develops from already existing glioma, about half of the patients demonstrate mutually exclusive MYC or MYCN amplifications." (PMID 33585252, 2020). "It is well known that MYC, as a proto‐oncogene, exhibits elevated levels of expression in most human tumours—including glioma—and promotes glioma growth." (PMID 32916774, 2020). "More biological and clinical studies are necessary to evaluate the utility of targeting the LINC00470/miR‐134/MYC/ABCC1 axis for the treatment of gliomas." (PMID 32916774, 2020). "All in all, we initially found that MYC induced HNF1A‐AS1 overexpression promoted glioma progression via modulating miR‐32‐5p/SOX4 axis, providing potent reference value for targeting HNF1A‐AS1 in future therapeutic strategies of glioma." (PMID 33448691, 2020). "In glioma, knockdown of KPNA2 decreased the levels of MYC and this was linked to decreased proliferation and invasion." (PMID 32512858, 2020). "Collectively, these data provided substantial proof for the activation of HNF1A‐AS1 transcription activity by MYC in glioma cells." (PMID 33448691, 2020). "The mammalian ortholog of brat, TRIM3, has similarly been shown to reduce MYC and promote differentiation in human glioma cell lines, while a reduced TRIM3 expression has been reported in glioblastoma and is associated with poor survival." (PMID 33092025, 2020). "Meanwhile, we confirmed that the protein expression of MYC in glioma was significantly up‐regulated and positively correlated with pathological grade." (PMID 32916774, 2020). "MYC effects on glycolytic metabolism have been demonstrated also in the setting of glioma, where glycolytic intermediate are used to fuel anabolic purine metabolism." (PMID 32932943, 2020). "In this study, we found elevated expression levels of LINC00470 and MYC in glioma tissues and cells and decreased expression of microRNA‐134 (miR‐134)." (PMID 32916774, 2020). "The level of MYC is positively related to cell number, which was confirmed in spheroids from a glioma cell line." (PMID 32046751, 2020). "In order to explore the downstream effectors of LINC00470 and miR‐134 in glioma cells, we predicted that MYC is the direct target of miR‐134 through bioinformatics analysis." (PMID 32916774, 2020).
glioma (continued). "As in neural stem cells, MYC likely promotes glioma by amplifying transcriptional programs promoting renewal and hampering differentiation." (PMID 33092025, 2020). "MYC and OCT4 are two canonical stem cell factors which are implicated in the development and progression of various solid tumors, especially glioma." (PMID 30795814, 2019). "Enrichment of MYC on the EGFR/EGFRvIII promoter region can notably facilitate the malignant phenotypes of glioma cells." (PMID 30795814, 2019). "Collectively, these results indicate that the aberrant activation of miR-9, especially of miR-9-2, in glioma cells is due to the enrichment of MYC/OCT4 on its promoter region." (PMID 30795814, 2019). "Moreover, multiple CNAs recurrently featured in ATRX-deficient glioma mobilize established oncogenic and/or tumor suppressive loci, including MYC and CDKN2A2, implying that such structural abnormalities may contribute to the malignant evolution of this inexorably progressive cancer." (PMID 30808951, 2019). "The significance of USP28 in glioma tumorigenesis has been demonstrated by its positive regulation on MYC, which is dysregulated in the majority of gliomas and difficult to target directly." (PMID 29415985, 2018). "Previous studies have focused on 8q, particularly 8q24 and c-MYC, which resides in the 8q24.21 region, in searches of human cancers, including gliomas." (PMID 29156679, 2017). "To test further the specificity of IGFBP2, we also analyzed MYC, FOXM1, and E2F2, which have been associated with malignant progression of IDH-mutant glioma." (PMID 27852048, 2017). "Screens including either grade II and grade III gliomas or pediatric HGGs have demonstrated amplifications of both c-MYC as well as MYCN, and in the context of pediatric HGG a clear association of MYCN amplifications with anaplastic astrocytomas was reported." (PMID 28333115, 2017). "A recent study has highlighted that the CSCs from glioma are more sensitive than the bulk tumor cells to cell death induced by MYC inhibition." (PMID 27821172, 2016). "A plausible explanation is that the effect exerted by rs55705857 shifts MYC expression only modestly and possibly only in a certain cell type, such as glioma initiating cells." (PMID 27282637, 2016). "On the other hand, inhibition of GSK3β activity results in c-MYC dependent glioma cell death through multiple mechanisms, all of which converge on the apoptotic pathways." (PMID 26437223, 2015). "MYC is known to regulate glutamine utilization and glutaminase protein expression, and mutant IDH gliomas are known to have an increased expression of MYC." (PMID 25376594, 2014). "Our data are in agreement with the central role of c-MYC in regulating glioma cancer stem cell proliferation." (PMID 24143218, 2013). "To determine this, we overexpressed IDH1-WT or one of five glioma-derived IDH1 R132 mutants with C-terminal MYC and FLAG tags in human oligodendroglioma (HOG) cells, a human glioma cell line that does not contain IDH mutations." (PMID 21326614, 2011). "Another m6A eraser, FTO, has been shown to promote glioma onset by targeting MYC mRNA." (PMID 40469294, 2025). "Moreover, all the genes comprising ESURATAG-GS have at least one binding site for MYC, suggesting their preferential regulation by MYC in gliomas." (PMID 40718795, 2025). "We sought to check whether MYC-driven regulation concommitantly aligns with aging and tumor aggressiveness in gliomas." (PMID 40718795, 2025). "In addition, MYC expression in glioma cells is induced by integrin α5β1-dependent JAK, and STAT3 activation, which follows, which in turn are regulated by stiff ECMs." (PMID 40124511, 2025). "MYC has already been shown to regulated tumor aggressiveness in gliomas." (PMID 40718795, 2025).
glioma (continued). "Finally, ESURATAG-GS exhibit high positive correlation with aging and EMT scores, and MYC-driven targets in 20 different glioma patient datasets, confirming that MYC-driven ESURATAG-GS lies at the heart of aging-related tumor aggressiveness in glioma patients." (PMID 40718795, 2025). "Genomic analysis of large cohorts of gliomas have also highlighted the prognostic value of PIK3CA mutation, TCF12 mutation and MYC pathway deregulation (by gene locus gain or gene promoter hypomethylation or by downregulation of MYC silencers which appear to be linked to unfavorable outcome in O3." (PMID 40315229, 2025). "In glioma cells, inhibition of LSD1 reduces signaling controlled by the stemness-associated gene MYC, which is regulated by super-enhancers; indeed, expression of MYC itself is downregulated following LSD1 inactivation." (PMID 39501082, 2024). "Furthermore, MYC boosts the ability of glioma stem-like tumor/tumorsphere cells to self-renew and increases their tumorigenic potential." (PMID 39606019, 2024). "Indeed, RNA sequencing (RNA-seq) analysis of H3-K27M-mutant patient-derived glioma cells (SU-DIPG13) treated with Sulfopin revealed strong enrichment of MYC targets among the downregulated genes." (PMID 39093942, 2024). "LncRNA LPP-AS2 promoted glioma tumorigenesis via a miR-7-5p/EGFR/PI3K/AKT/c-MYC feedback loop." (PMID 38725030, 2024). "Copy number gains of MYC are commonly observed in IDH-mutant gliomas." (PMID 38877600, 2024). "High-level gene amplification of MYC is recurrently observed in pediatric high-grade gliomas." (PMID 39093942, 2024). "This study established a co-expression relationship between MYC and ABCC1, and that overexpression of MYC could increase ABCC1 levels in glioma cells." (PMID 39403602, 2024). "Pivotal studies suggest that MYC inhibition could prevent glioma formation, blocking cell proliferation and survival and even inducing disease regression." (PMID 38333013, 2024). "In this way, MYC continues to accumulate, eventually leading to the proliferation of gliomas." (PMID 38125749, 2023). "Furthermore, knockdown of Ezh2 in glioma cells was found to upregulate 85 miRNA genes, many of which are also known to be repressed by MYC." (PMID 37908640, 2023). "In gliomas, c-MYC plays a central role in tumorigenesis and progression." (PMID 38017538, 2023). "Furthermore, we found that ptc-miR396f-mediated targeting of apoptosis-related genes in GENs exerted a significant gene silencing effect on the c-MYC, resulting in the suppression of tumor growth and prolonged survival rate in a glioma-bearing mice in vivo." (PMID 37542285, 2023). "Comparatively, FTO may encourage the proliferation of glioma cells by upregulating the levels of MYC, miR-155, and miR-23 through the MYC-miR-155/23a cluster-MXI1 positive feedback loop." (PMID 38125749, 2023). "The expression of MYC has also been shown to correlate with glioma grade." (PMID 37400829, 2023). "Therefore, the E2F-1/MAD2L2/c-MYC axis facilitates the stemness and aggressive behaviors, such as proliferation and invasion, in glioma, providing new insights for the treatment of this disease." (PMID 38017538, 2023). "Analysis of multiple glioblastoma-related datasets from GEO demonstrated a positive correlation between MAD2L2 expression and the MYC pathway, indicating that MAD2L2 may influence glioma growth and stemness by affecting c-MYC activity." (PMID 38017538, 2023). "Overexpression of MYC in gliomas was further shown to be related to increasing tumor grade." (PMID 36361720, 2022). "The level of MYC had lower expression in glioma than normal tissues (#Antibody CAB010307)." (PMID 36527013, 2022). "Our combined data showed that CTD inhibited the MZF1/c-MYC axis in glioma cell proliferation." (PMID 36499054, 2022).
glioma (continued). "For instance, a study conducted with the primary goal of identifying long non-coding RNA and clarifying its function and mode of action in glioma formation showed that LPP Antisense RNA 2(LPP-AS2) promotes glioma carcinogenesis through a miR-7-5p/EGFR/PI3K/AKT/c-MYC feedback loop." (PMID 35619711, 2022). "MYC promotes both glycolytic flux and glutamine levels in glioma cells of GBM." (PMID 35158782, 2022). "Furthermore, GSK343 treatment in normal glioma cells not only reduced the protein quantities of EZH2 but also downregulated the secretion of c-MYC." (PMID 34745848, 2021). "Besides, FBXW7, among other ligases, modulates the proteasomal degradation of MYC, an oncological transcriptional factor generally overexpressed in gliomas." (PMID 33665742, 2021). "Both SIX1 and MYC were upregulated in patients with glioma with amplified enhancer." (PMID 33537074, 2021). "Notably, MYC can bind to the EGFR/EGFRvIII promoter region to increase the malignant phenotype of glioma cells." (PMID 34646821, 2021). "Thus, lncRNA LPP-AS2 promoted glioma tumorigenesis via a miR-7-5p/EGFR/PI3K/AKT/c-MYC feedback loop." (PMID 32962742, 2020). "Furthermore, in glioma, the work by Rich and colleagues showed that MYC can upregulate the anabolism of mevalonate, a crucial lipid for cholesterol biosynthesis." (PMID 32932943, 2020). "Furthermore, in the MYC-expressing human adult high-grade glioma cell line U305628 we again observed a significant downregulation of CCNB1 after 6 h of BRD4 inhibition via JQ1." (PMID 32843692, 2020). "In order to clarify whether MYC was involved in the tumour‐promoting role of LINC00470, we analysed the expression level of MYC in LINC00470‐overexpressing glioma cells." (PMID 32916774, 2020). "Collectively, these data suggested that the c-MYC transcriptionally regulated lncRNA LPP-AS2 was highly expressed in glioma tissues, and might be a promising indicator of glioma prognosis." (PMID 32962742, 2020). "Furthermore, MYC was positively correlated with ATP‐binding cassette subfamily C member 1 (ABCC1) expression in glioma cells and MYC up‐regulated ABCC1 expression." (PMID 32916774, 2020). "Besides, in our study, we also confirmed that the mRNA expression level of MYC was elevated in glioma tissues." (PMID 32916774, 2020). "MYC is involved in the regulation of proliferation and survival of glioma cancer stem cells." (PMID 32604718, 2020). "Indeed, reverse genetics experiments on glioma cell lines revealed that MYC directly regulate the transcription of high affinity glutamine importers, which are fundamental for glioma cell survival." (PMID 32932943, 2020). "MYC is a member of the helix‐ring‐helix superfamily, which functions as a transcription factor and is highly expressed in various human tumours including gliomas." (PMID 32916774, 2020). "Our study further confirmed the up‐regulation of MYC at both mRNA and protein levels in gliomas." (PMID 32916774, 2020). "Moreover, the reduced expression patterns of stemness-associated genes (MYC and SOX2) and the reactivation of neuronal differentiation-associated genes (BDNF, NGF, and NTF3) were clearly observed in the asTUG1/uPIC-treated glioma tissues." (PMID 31019193, 2019). "In addition, maintenance of miR-9 in glioma cells depends on direct activation by MYC or OCT4 on the miR-9 promoter." (PMID 30795814, 2019). "The oncogene MYC can bind to the promoter region of other oncogenes such as some miRNAs; for example, miR-9 is frequently upregulated in glioma specimens and cells, and it could significantly enhance proliferation, migration, and invasion of glioma cells." (PMID 31921661, 2019). "Nevertheless, MYC resulted to be overexpressed in these pediatric glioma xenografts." (PMID 29258209, 2017). "Considering the well-known roles of MYC in various cancer types including gliomas and its relative proximity to rs55705857 on chromosome 8, we hypothesized that rs55705857 may modulate MYC expression." (PMID 27282637, 2016).